CD4 (CD4 molecule)
Diseases named in the same sentence as CD4 in open-access papers (continued):
Sharing a sentence is not in itself a finding about the gene and the disease.
tumor (continued). "We discovered that the protein TMEM123 is over-expressed in tumour-infiltrating CD4 and CD8 T lymphocytes and it contributes to their effector phenotype." (PMID 37426665, 2023). "In vitro, CD4+ CAR T cells demonstrated similar cytotoxicity to CD8+ CAR T cells against tumor cells, albeit at a lower level." (PMID 38328405, 2023). "In transgenic mice IMQ promoted breast cancer tumour regression, which progressed at the end of treatment due to CD4+ cells augmentation that enhanced IL-10 levels." (PMID 38077402, 2023). "CXCR6-deficient mice have an apparent higher tumor burden and tumor progression after intraperitoneal injection of DEN due to a reduction of iNKT and CD4 + T cells in the liver." (PMID 36773210, 2023). "Tumoral MHC-II protein expression, which is known to trigger CD4+ T cell-mediated responses, is associated with immune-mediated tumor suppression and increased responsiveness to immunotherapies." (PMID 36690875, 2023). "Studies have reported similar results, in addition to tumor regression, decreased lung metastasis, and increased systemic CD4+ and CD8+T cells, cryoablation was also accompanied by an increase in NK cells." (PMID 36761748, 2023). "CD4+CD25+Foxp3+ regulatory T cells (T reg cells) similarly promoted tumor immune escape and CD4+ Th17 cells promoted PDA epithelial cell proliferation." (PMID 37081882, 2023). "Soluble antigens secreted by tumor cells are presented to CD4+ T cells by antigen-presenting cells, activating the CD4+ T cells." (PMID 36797245, 2023). "Our results showed that the proportion of tumor immune cells (B cells, CD4+ T cells, CD8+ T cells, neutrophils, macrophages, and dendritic cells) was significantly correlated with PPRC1 expression in 33 out of 38 tumor types." (PMID 37109742, 2023). "Basically, each animal had a private set of high-frequency tumor-responding CD4 and CD8 TCR clonotypes." (PMID 37033929, 2023). "Under inflammatory conditions, galectin-4 suppresses tumor growth by stimulating memory CD4+ T cell expansion." (PMID 36873388, 2023). "More importantly, elicited immunity was confirmed by identifying increases in tumor-infiltrating CD4+ and CD8+ T cells in the KO exosome group." (PMID 36650153, 2023). "In particular, the expression of ER and AR showed a negative correlation not only with total immune content in the tumor microenvironment but also with certain immune cell subsets such as macrophages and CD4+ T cells." (PMID 36721218, 2023). "While cytotoxic CD8+ and CD4+ T lymphocytes directly contribute to tumor cytotoxicity through secretions of perforin and granzyme cytokines, Tregs have the opposite effect." (PMID 37345111, 2023). "This combination therapy also reduced tumor burden in various organs of the studied mice and increased the frequency of effector CD4+ and CD8+ TILs in the TME." (PMID 36618103, 2023). "Levels of tumor-infiltrating CD4+ T cells were only significantly higher in HUSOV1 compared to the other groups." (PMID 37949944, 2023). "Infiltrating immune cells, such as CD8 + T cells, B cells, CD4 + T cells, and NK cells, secrete various factors that influence the tumor microenvironment, regulate tumor behaviors, and have anticancer properties." (PMID 37117215, 2023). "Flow cytometric analyses of tumour-infiltrating CD45+ cells at day 7 after adoptive T cell transfer revealed a comparatively small subpopulation of adoptively transferred TRP-1 CD4+ T cells representing only 1% of immune cells in treated mice." (PMID 37316667, 2023). "Accordingly, we evaluated the expression of the PODO447 tumor glycoepitope and the number of CD4+, CD8+ and CD3+ T cells and CD20+ B cells/plasma cells via multiplex IHC staining of Cohort D." (PMID 38188285, 2023). "When encountering an antigen, naive CD8+ and CD4+ T cells differentiate into effector cells, which migrate to the site of infection or the tumor." (PMID 37529035, 2023).
tumor (continued). "As for cDC2s, the presentation of tumor antigens directly to CD4 T-cells—needed for CD8 T-cell activation—or indirectly by transferring tumor antigens to lymph node resident cDC2s represent the major roles of cDC2s in anti-tumor immunity." (PMID 37190135, 2023). "Higher levels of CD4+ T lymphocytes can reduce the risk of recurrence, while lower levels of CD4+, CD8+, CD3+, and CD56+ T cells in advanced tumors reduce the lymphocyte-mediated anti-tumor cellular immune response, ultimately leading to worse prognosis." (PMID 37444448, 2023). "In mouse models of PDAC, intra-tumor radiofrequency ablation (RFA) reduced tumor progression by increasing neutrophil and dendritic cell infiltrate and by promoting a significant CD4+ and CD8+ T cell abscopal response." (PMID 37509365, 2023). "pp65 is a major cytomegalovirus (CMV) protein that provides exceptional tumor specificity for glioblastoma and is designed to stimulate pp65-specific CD4+ and CD8+ T cell response." (PMID 37420174, 2023). "CD4+ T cells are essential in the defence against tumours because they regulate the activity of CD8+ T cells and influence the outcome of antitumour responses." (PMID 37480104, 2023). "We observed that PD-1lowCD4 T cells enhanced the in vitro cytotoxic activity of tumor-infiltrating CD8 T cells isolated from TC-1 tumor against CFSEhigh-labeled TC-1 target cells compared to PD-1high CD4 T cells." (PMID 37147330, 2023). "An enhancement of tumor-infiltrating CD4+ T cells was observed in Mito-ATO-treated cells and increased the anti-tumor activity of Programmed Death 1(PD-1) blockade immunotherapy." (PMID 37954849, 2023). "The number of tumor-infiltrating CD4+ T cells decreased significantly (CCR4−/−: 488 ± 72 CD4+ cells per 1 × 105 tumor cells vs. WT: 1538 ± 355 CD4+ cells per 1 × 105 tumor cells; n = 9, p = 0.0074) with a mean absolute reduction of 1050 ± 343 (72.5%)." (PMID 37371612, 2023). "CD4 +T cells are essential components of the anti-tumor immune response as they stimulate CD8+ T cells and induce DCs to express CD40 ligand." (PMID 38089966, 2023). "Injection of AMP-IBP5 into the skin lesions of AD mice also noticeably reduced the numbers of CD4+ T cells and mast cells and the total serum immunoglobulin (Ig) E level." (PMID 36982275, 2023). "Specifically, we found that ICB+DT induced a clear trend toward increased frequency of CD8+ T cells in the tumor and a statistically significant increase in the frequency of CD4+ Thelper cells and CD4+CD8+ T cells." (PMID 37089449, 2023). "Validation of these clinical findings in murine models revealed increased anti-tumour immunity as well as increased CD4 and CD8 T-cell infiltration." (PMID 37894393, 2023). "Antigen-presenting cells showed tumor antigens to CD4 T regulatory (Treg) cells, which indirectly made CD4 T regulatory (Treg) cells." (PMID 36891324, 2023). "When we examined T cells viability in the tumor region, we found that T cells expansion were significantly increased with miR-375 overexpression, both CD4+ T and CD8+ T cells showed an increasing trend." (PMID 38093288, 2023). "An upsurge in Treg cells can facilitate tumor immune escape, while activation of FOXP3+CD25+CD4+ Treg cells can markedly dampen tumor immune response." (PMID 37920470, 2023). "For instance, in a xenograft mouse model of HCC, abrogation of the WNT secretion of tumor cells by knockdown of WLS decreased the proportion of tumor-infiltrating TAMs and Treg cells and increased the proportion of CD4+ and CD8+ T cells." (PMID 36982422, 2023). "After normalizing for tumor weight, Ero1aKO tumors showed higher proportions of CD4+ T, CD8+ T, and NK cells, suggesting ERO1A impedes lymphocyte infiltration." (PMID 37769655, 2023). "Melanoma cells with active VDR signaling and a suppressed Wnt-beta catenin pathway show increased tumor antigen release, antigen presentation, CD4+ T cell activation and priming, and increased CTL and NK infiltration and tumor cell killing." (PMID 37175993, 2023).
tumor (continued). "Meanwhile, in the low‐risk group, higher proportions of anti‐tumor immune cells, such as T cell CD8+, T cell follicular helper, B cell plasma, T‐cells‐CD4‐memory‐resting, and T cell CD4+ memory activated were observed." (PMID 35616307, 2023). "It was confirmed by further experiments that after depletion of CD8+ T cells, PDT treatment reduced the tumor cure rate from 100% to 50%, with a more significantly impact than CD4+ T cells depletion." (PMID 38004595, 2023). "This highest frequency oligoclonal response in spleen varied from 2-18 CD8 and 0-5 CD4 T-cell anti-tumor TRA or TRB clonotypes per animal (median CD8 = 2.5 and CD4 = 1.5)." (PMID 37033929, 2023). "The same trends were observed when the tumor-rich stroma-free regions for CD4+ and CD8+ T cells were examined." (PMID 38188285, 2023). "Unlike the traditional activation pathway of M1 macrophage which was mainly mediated by IFN-γin TME of LSCC, the activation level of M2 TAM depended mostly on the complex immune microenvironment of tumor, especially the co-reaction of CD4+ T cell/MHC-II axis." (PMID 36864443, 2023). "Within the TME, IL-1Ra is capable of suppressing the immunogenic anti-tumor response by impairing the activities of APCs, CD4+ T cells, and CD8+ T cells." (PMID 37563620, 2023). "CD8+ cytotoxic and CD4+ helper T cells are important by expressing effector programs against tumour antigens." (PMID 37853118, 2023). "FOXP3+CD4+ Tregs mostly exist in the blood, whereas CTLA4+CD4+ Tregs clone and amplify locally within tumors, indicating local clonal expansion of tumor-resident Tregs." (PMID 37187731, 2023). "Tumor-specific CD8+ T cells and CD4+ T cells are required for the effective clearance of tumor cells." (PMID 37124063, 2023). "In the low-TEXPM group, there were more activated memory CD4+ T cells, M1 macrophages (anti-tumor phenotype), and CD8+ T cells, while the high-TEXPM group had more M2 macrophages (pro-tumor phenotype)." (PMID 37354485, 2023). "T follicle helper (Tfh) cells, a subset of CD4+ T cells, are responsible for directing and activating tumor-specific B cells and T cells, thereby promoting the formation and enhancement of anti-tumor immunity." (PMID 38187373, 2023). "In this study, tumor formation was controlled by vaccine-induced CD4+ T cells and this control was abrogated by anti-CD4 antibody administration." (PMID 37965314, 2023). "Studies have proved that these exosomes carrying tumor antigens can stimulate CD4+ and CD8+ T cells, producing adaptive immune responses and anti-tumor T cell responses, leading to the shrinkage of the tumor cells." (PMID 38188673, 2023). "We also examined the association between the expression of cGAS-STING in tumor cells and the infiltrations of CD8+ T cells and CD4+ T cells in pMMR CRC." (PMID 37345163, 2023). "These CD4+ subsets have autologous tumor cell killing abilities (as they secrete TNF-α and IFN-γ) ex vivo." (PMID 38328405, 2023). "Populations of CD3+ T cells and the ratio of CD4+/CD8+ T cells in the peripheral or tumor microenvironment were quantified to assess the immune response to allograft tumors." (PMID 37205112, 2023). "Expression of TIGIT and TIM-3 on trNK cells, and all immune checkpoint receptors analyzed on CD8+ TRM and CD4+ TRM cells increased toward the tumor center." (PMID 37448786, 2023). "Within this framework, Th1-like helper CD4 T cells have been shown to be important for effective priming of anti-tumor CD8 T cells while CD4+ regulatory T cells have been shown to impede priming and effector function of anti-tumor CD8 T cells." (PMID 37654482, 2023). "Most of the immune cells were distributed in the tumor stroma, and only a small group of CD4/CD8 T cells were in the tumor parenchyma." (PMID 36891293, 2023). "To further explore the potential effects of RIME on other immune cells infiltrating the tumour microenvironment, we performed flow cytometry analysis of CD4+ T cells, M1 macrophages, M2 macrophages, and NK cells in the xenografts." (PMID 37712124, 2023).
tumor (continued). "DCs, CD4 + T helper (Th) cells, and CD8 + cytotoxic T-lymphocytes (CTL) play a central role in antitumor immunity and are significantly associated with tumor prognosis." (PMID 36966334, 2023). "CD8+ and CD4+ T cells play a vital role in the killing of tumor cells, both in terms of their direct anti-tumor activity and their support for the immune response." (PMID 37107299, 2023). "B cells directly present tumor-associated antigens to CD4+ T cells and CD8+ T cells, produce antibodies to promote the uptake of tumor antigens by TAMs and DCs, and secrete cytokines to promote antitumor immunity or directly kill tumor cells." (PMID 37275909, 2023). "T lymphocytes, such as CD4+ cells, usually play a crucial role in the tumor immune response including releasing immunoregulatory factors, inhibiting tumor growth and metastasis, and other processes." (PMID 37251954, 2023). "Three model features correlated with clinical outcomes in an independent cohort: granulocyte MAPKAPK2 signaling at the tumor front, stromal CD4+ memory T cell size, and the distance of fibroblasts from the tumor border." (PMID 38125025, 2023). "In our RCC samples, the expansion potential was inversely correlated with the CD4+ T cell phenotype in the tumor." (PMID 37484198, 2023). "Surprisingly, we noticed that both CD8+ and CD4+ cells expressing exhaustion features were located in closer proximity to the tumor cells spatially." (PMID 38123589, 2023). "Shp2f/fLysMCre tumor-bearing mice also exhibited enhanced T cell activation and recruitment of CD4+ and CD8+ TEF cells in dLN." (PMID 36581713, 2023). "Memory CD4 T-cells are certainly present and necessary for an effective anti-tumor response, as shown in our previous work." (PMID 37033929, 2023). "ICP-targeted mAbs aim to stimulate CD8 + and CD4 + FoxP3- anti-tumor T-cells while inhibiting immunosuppressive CD4 + FoxP3 + regulatory T-cells." (PMID 38057799, 2023). "A similar trend was observed in the relative frequencies of IFNγ+ CD4+ to IL-17A+ CD4+ T cells (Tumor 9.7% versus 5.5%; STM 8.2% versus 1.3%)." (PMID 38074634, 2023). "The ability of CD4+ CAR T cells (CAR4 T cells) to induce tumor regression has been shown to be highly variable in distinct preclinical models of B-cell malignancies or solid tumors." (PMID 37248395, 2023). "Due to a simultaneous stimulation by IL-2 and TGF-β, and the expression of the high affinity IL-2 receptor, T cells are more likely to differentiate into CD4+ Treg cells that protect the tumor by consuming IL-2 and secreting IL-10 and TGF-β." (PMID 37238744, 2023). "It has been found that peripheral CD4+CXCR5+ T cells participate in the pathogenesis and progress of OS, and patients with high tumor grade show a significant increase in the percentage of CD4+CXCR5+ T cells compared with patients with low OS grade." (PMID 37064862, 2023). "Later, the term ‘agranular CD4+CD56+ hematodermic neoplasm/tumor’ was deployed based on the immunophenotype and the tendency for skin involvement." (PMID 37026111, 2023). "A higher proportion of CD4+ Th17 cells has been found in the tumor tissue than in the peripheral blood of BC patients." (PMID 36614308, 2023). "Several studies have demonstrated that bacteria at the tumor site can induce a large number of immune cells to accumulate toward the tumor, including macrophages, NK cells, B cells, CD4+ T cells, CD8+ T cells, and so on." (PMID 37765183, 2023). "The majority of liver infiltrating CD8+ and CD4+ T cells in non-tumor bearing animals had minimal expression of either Tim-3 or PD-1, although there was a small but detectable population of Tim-3+/PD-1+ CD4+ T cells." (PMID 38045348, 2023). "Compared with CD8+ T cells, CD4+ T cells easily infiltrate and proliferate in tumour tissue, highlighting their importance in antitumour immunity." (PMID 37471521, 2023).
tumor (continued). "Further, the average percentage of tumor-infiltrated CD4+ T cells and CD8+ T cells were 30% and 70% respectively, which was consistent with the principle of more CD8+ T cells to kill tumor cells." (PMID 37481592, 2023). "In TIMER, the high-risk group exhibited elevated expression levels of anti-tumor immune cells, encompassing CD8+ T cells, CD4+ T cells, B cells, macrophages, and dendritic cells." (PMID 37629096, 2023). "We found that a higher number of Foxp3+ T cells and higher Foxp3/CD4 and Foxp3/CD8 ratios at the invasive front of the tumor were associated with LN metastasis." (PMID 37958412, 2023). "The inhibition of FXR by norcholic acid upregulates PD-L1 on the surfaces of HCC cells and tumor-derived exosomes, which dramatically dampens the function of CD4+ T cells, resulting in an immunosuppressive tumor microenvironment." (PMID 38203175, 2023). "Conjugation between DN B cells and CD4+ CTLs was observed in extrafollicular sites adjacent to tumor cells." (PMID 38077321, 2023). "The correlations between SOX4 expression and the immune infiltrating cells (including CD8+ T cells, CD4+ T cells, B cells, neutrophils, macrophages, and myeloid dendritic cells) across various tumor types were visualized using cluster heatmaps." (PMID 37958409, 2023). "Since the hypoxic tumor microenvironment is a key obstacle impeding T cell stimulation, thus we postulated that simultaneous PD-L1 blockade and CD4+ T cell depletion promotes tumor vascular normalization." (PMID 36969495, 2023). "An increasing trend was noted also in the number of CD4+ T cells stained for TIM3 or LAG3 in tumor of SR59230A, αPD-L1 treatments and their combination, but they failed to reach statistical significance." (PMID 36854895, 2023). "Summarily, S15+ tumor cells or TAMs were spatially closer to CD4+FoxP3+ Tregs, and S15+ tumor cells were positively correlated with the spatial density of TAMs, and spatially closer to TAMs." (PMID 37674198, 2023). "It was already observed in a mouse model study, that splenic GrMDSCs strongly suppress CD4+ T-cell proliferation while the suppressive effect on CD8+ T cells is less pronounced compared to tumour GrMDSCs." (PMID 36899926, 2023). "Robust and functional CD4+ T cell responses are essential for effective pathogen clearance and tumor eradication." (PMID 37332039, 2023). "Functional alterations in subsets of human tumor-induced senescent CD4+ T cells, which inhibit the proliferation of responder T cells through the cell-to-cell contact, are tumor-promoting mechanisms." (PMID 37059592, 2023). "Further analysis revealed that naïve T cell populations significantly decreased in tumor-infiltrating CD4 cells (p 0.04) as well as in the blood (p 0.0002)." (PMID 36251031, 2023). "Together these data show that HER2 CAR T cells provide a robust anti-tumor response in SU-DIPG36 facilitated by strong CD4+ and CD8+ T cell engraftment and infiltration of the brain." (PMID 37152812, 2023). "The recruitment and activation of CD4+ T lymphocytes are related to establishing a tumor immunosuppressive microenvironment." (PMID 37205181, 2023). "Pant-treated D20 samples contained twofold more NK/ILC, CD4+ in the tumor and OVA-specific effector CD8+ T cells in the tumor-draining lymph nodes (TDLNs)." (PMID 37833072, 2023). "The roles of CD4+T cells, CD8+T cells and tumor associated macrophages (TAMs) on clinical outcomes prediction were investigated." (PMID 38082307, 2023). "This combination approach also augmented the ratio of CD8+/CD4+ T cells in lymph tissues adjacent to tumor sites at mouse mammary glands, which is considered an important marker of immunological defense against tumor cell dissemination." (PMID 38268926, 2023). "Second, only CD3 and CD8 were used for this study; more research is required on other biological markers of tumor cells, such as CD4 and FOXP3." (PMID 36860311, 2023).